KIAA1549 (KIAA1549)
Description:
May play a role in photoreceptor function.
Synonyms: RP86
Tractability: Antibody: its Gene Ontology location is reachable by antibodies, with high confidence; UniProt predicts a signal peptide or a membrane-spanning region. PROTAC: ubiquitination databases record sites on it.
Gene: Protein-coding gene on chromosome 7 (138,831,381 to 138,982,084, reverse strand). Ensembl gene ENSG00000122778.
Subcellular location: Membrane; Cell projection, cilium
Subcellular location (Human Protein Atlas): Nuclear membrane; Intermediate filaments
Pathways (Reactome):
Disease: Signaling by BRAF and RAF1 fusions
Gene Ontology:
Molecular function: protein binding
Cellular component: photoreceptor connecting cilium; plasma membrane; cilium; membrane
Genetic constraint (gnomAD): Loss-of-function variants: 65 observed, 136.81 expected, observed/expected ratio (o/e) 0.48, 90% interval 0.39 to 0.58. The upper end of that interval is the gene's LOEUF score, 0.58, which puts it in group 2 of 6, group 1 being the genes least tolerant of losing a copy. Missense variants: 2,297 observed, 2,439.8 expected, observed/expected ratio (o/e) 0.94, 90% interval 0.91 to 0.97. Synonymous variants: 1,035 observed, 1,020.4 expected, observed/expected ratio (o/e) 1.01, 90% interval 0.96 to 1.07.
Gene-disease validity (ClinGen):
ClinGen rates the evidence that KIAA1549 causes each of these diseases.
retinitis pigmentosa 86 (autosomal recessive): Strong.
Homologues: Orthologues: chimpanzee KIAA1549 (98% identical), macaque KIAA1549 (95% identical), mouse D630045J12Rik (72% identical), rat Kiaa1549 (72% identical), dog KIAA1549 (71% identical), pig KIAA1549 (71% identical), rabbit KIAA1549 (68% identical), guinea pig KIAA1549 (61% identical). Paralogues in human: KIAA1549L (21% identical).
Diseases named in the same sentence as KIAA1549 in open-access papers:
KIAA1549 is named in the same sentence as 51 diseases in open-access papers, as found by Europe PMC text mining. Sharing a sentence is not in itself a finding about the gene and the disease. The quoted sentences say what the papers report.
pilocytic astrocytoma (76 papers, 2013 to 2026). Pilocytic astrocytoma is a rare subtype of low-grade glioma of the central nervous system characterized by a well circumscribed, often cystic, brain tumor with a discrete mural nodule and long, hair-like projections that extend from the neoplastic astrocytes. "In ganglioglioma recurrence, the genetic studies shoved the mutation BRAF6V600E, and the KIAA1549-BRAF fusion transcript was expressed in the pilocytic astrocytoma." (PMID 40731067, 2025). "The KIAA1549::BRAF fusion has been described in pilocytic astrocytoma, where it is associated with a favorable prognosis, and in pediatric low-grade astrocytoma." (PMID 39324010, 2024). "The only alteration associated with improved survival was KIAA1549, as expected given its association with pilocytic astrocytoma." (PMID 36854806, 2023). "BRAF alterations included KIAA1549-BRAF fusion that is more specific of pilocytic astrocytomas (5 cases) and the BRAF V600E mutation that is more frequent in ganglioglioma (4 cases)." (PMID 37936887, 2023). "Regarding KIAA1549-BRAF fusion in pilocytic astrocytomas and diffuse astrocytomas, there was an association between the fusion and its anatomical location to the cerebellum (Chi square test; P = 0.04)." (PMID 35363819, 2022). "Further analyses of these samples by additional NGS panels revealed KIAA1549–BRAF fusion in six pilocytic astrocytomas and one PTPN11 mutation in the glioneuronal tumor." (PMID 31167453, 2019). "We analysed the location of one such mutation involving exons 8–16 of the KIAA1549 gene fused to the C-terminal domain (exons 9–18) of BRAF (SK:B) reported in human pilocytic astrocytomas." (PMID 30603699, 2018). "Gangliogliomas more frequently harbor BRAF p.V600E mutation or other variant BRAF mutations than pilocytic astrocytomas, which most commonly harbor KIAA1549-BRAF fusion." (PMID 29880043, 2018). "The protein encoded by KIAA1549 has been found to be fused to the BRAF oncogene in many cases of pilocytic astrocytoma." (PMID 26132924, 2015). "The KIAA1549:BRAF fusion gene was initially thought to be highly specific for pilocytic astrocytomas thereby suggesting a useful diagnostic biomarker for a tumor with varied and challenging histology." (PMID 24716189, 2014). "One recent study of 51 pilocytic astrocytomas suggests that the presence of a KIAA1549:BRAF fusion should be associated with a pilocytic classification, while a BRAF V600E mutation is more prevalent in non-pilocytic gliomas." (PMID 23717811, 2013). "Given the presence of the KIAA1549-BRAF gene fusion in over 67% of our pilocytic astrocytoma cases, it could be more of a useful diagnostic tool for this entity, than a prognosis related marker." (PMID 35363819, 2022). "However, we think LGALS3 only has limited auxiliary diagnostic ability due to emerging molecular markers, such as IDH mutation, 1p/19q codeletion, and BRAF-KIAA1549 fusion (pilocytic astrocytoma's characteristic molecular alteration)." (PMID 32528967, 2020). "One pontine DMG harbored a KIAA1549::BRAF fusion, a molecular alteration associated with pilocytic astrocytoma and diffuse leptomeningeal glioneuronal tumor and exceedingly rare in DMGs." (PMID 40237561, 2025). "In our series, the mutations V600-BRAF and the KIAA1549-BRAF fusion were detected in gangliogliomas and in pilocytic astrocytomas." (PMID 40731067, 2025). "Notable mutations driving these tumours include the KIAA1549‐BRAF fusion, which is common in pilocytic astrocytoma (approximately 70%) and rosette‐forming glioneural tumours (around 30%) in non‐NF1 cases." (PMID 40735832, 2025). "The KIAA1549-BRAF fusion gene is prevalent in pilocytic astrocytomas, but its presence in RGNTs is unclear." (PMID 39457636, 2024). "BRAF fusions with KIAA1549 as a partner gene were observed in 3 patients, all of which were diagnosed with pilocytic astrocytomas." (PMID 39143272, 2024).
pilocytic astrocytoma (continued). "The KIAA1549:BRAF fusion gene is considered a driver in pilocytic astrocytoma, and constitutively activates the MAP kinase pathway." (PMID 38791993, 2024). "One spinal tumor (case #2) in this group contained areas reminiscent of pilocytic astrocytoma and harbored KIAA1549::BRAF fusion together with ATRX loss being highly suggestive of HGAP7." (PMID 37891325, 2023). "For example, only 21.1% of the recurrent KIAA1549-BRAF fusion in pilocytic astrocytoma and 24.4% of ERG-TMPRSS2 in prostate adenocarcinoma led to neoantigens." (PMID 37461029, 2023). "BRAF-KIAA1549 (B-K) fusion was only detected in pilocytic astrocytoma and tumors histologically classified as diffuse astrocytoma." (PMID 36319795, 2022). "Seventeen fusions confirmed or corresponded to the initial diagnosis, for example, the COL3A1-PLAG1 fusion in a lipoblastoma and the KIAA1549-BRAF fusions in two pilocytic astrocytomas." (PMID 35085008, 2022). "Two pilocytic astrocytoma samples were false negatives for the KIAA1549-BRAF fusion because of suboptimal design of the RT-PCR primer positions, and the COL3A1-PLAG1 fusion was missed by FISH in two lipoblastoma samples." (PMID 35085008, 2022). "These cases included an optic pathway/hypothalamic glioma (EOR = 64%), a focal brainstem glioma (KIAA1549-BRAF fusion pilocytic astrocytoma) (EOR = 78%), and a diffuse midline glioma with H3K27M alterations (EOR = 31%)." (PMID 36686826, 2022). "Not only did RNA-seq detect common fusions such as BRAF-KIAA1549 in 4 pilocytic astrocytomas, but it also detected rarer fusions including 2 cases with NTRK fusions, and one with a clear MYBL1 driver in an infiltrating astrocytoma." (PMID 35475276, 2022). "In two of these tumours, duplication of the 3′ red signal was observed, suggesting the presence of the common KIAA1549:BRAF tandem‐duplication characteristic of pilocytic astrocytoma." (PMID 35836307, 2022). "We used the ddPCR approach reported by Appay and co-workers to investigate DNA extracted from FFPE samples of pilocytic astrocytomas of 20 patients for BRAF duplication as a surrogate marker for KIAA1549-BRAF fusions." (PMID 35361262, 2022). "have noted that the frequency of KIAA1549-BRAF fusions in spinal pilocytic astrocytomas is lower than the reported frequency in their intracranial counterpart." (PMID 36147920, 2022). "When exploring the prevalence of BRAF alterations in different subtypes, KIAA1549:BRAF fusion and BRAF V600E mutations were seen in 50–85% and 9-15% of pilocytic astrocytomas, respectively and were mutually exclusive." (PMID 34360713, 2021). "For example, a tandem duplication event linking BRAF to a nearby gene, KIAA1549, is a recurrent event seen in a majority of pilocytic astrocytomas and represents the predominant neoplastic driver in such cases." (PMID 32493417, 2020). "The KIAA1549/BRAF fusion was detected in 1 out of 8 pilocytic astrocytomas in our cohort and in two grade II astrocytomas (all 3 in methylation cluster PA-like)." (PMID 32555164, 2020). "For other brain tumors, it was interesting to find that in pilocytic astrocytoma (PA) cases with KIAA1549-BRAF fusions, more CTCs were recruited than those in wild-type cases." (PMID 33208163, 2020). "Pilocytic astrocytomas are grade 1 tumors usually occurring in children and young adults with KIAA1549-BRAF fusion defining the majority of pilocytic astrocytomas." (PMID 31355086, 2019). "Because of the high frequency of BRAF fusions, a patient-derived KIAA1549:BRAF-driven pediatric pilocytic astrocytoma model has been established for preclinical drug testing and has been used for selected MAPK and MEK inhibitor testing." (PMID 31181803, 2019). "Similar results were obtained using ΔBRAF tagged with the hormone-binding domain of the oestrogen receptor (hbER) and with the KIAA1549-ΔBRAF translocation mutant found in human pilocytic astrocytomas." (PMID 30603699, 2018).
pilocytic astrocytoma (continued). "KIAA1549-BRAF fusions are particularly frequently seen in pilocytic astrocytomas, a low grade, predominantly paediatric tumour arising most commonly in the posterior fossa." (PMID 29098416, 2018). "One study of posterior fossa and spinal cord gangliogliomas with a glial component resembling pilocytic astrocytoma found that a subset harbored KIAA1549-BRAF fusion that the authors referred to “pilocytic astrocytoma with focal gangliocytic differentiation”." (PMID 29880043, 2018). "An important differential diagnosis to this tumour is the pilocytic astrocytoma, which can have similar histological features (for example, clear cell morphology and leptomeningeal spread) and often harbours the KIAA1549–BRAF fusion." (PMID 29098416, 2018). "KIAA1549-BRAF fusion is the most common genetic event in pilocytic astrocytoma (PA), and leads to activation of the mitogen activated protein kinase (MAPK) signaling pathway." (PMID 29141672, 2017). "DNA methylation array and KIAA1549:BRAF fusion analysis confirmed pilocytic astrocytoma identity of DKFZ-BT66 cells after establishment." (PMID 28002790, 2017). "Recent studies have shown that some pilocytic astrocytomas carry duplication at chromosome band 7q34 containing a BRAF-KIAA1549-gene fusion." (PMID 27313931, 2016). "In pilocytic astrocytomas (WHO grade I), we detected gain of chr7q34, which was associated with the presence of the KIAA1549:BRAF gene fusion, as recently reported by our group via FISH assay on these samples." (PMID 27172220, 2016). "All the pilocytic astrocytomas used in the test cohort contain the KIAA1549-BRAF fusion that activates the ERK/MAPK pathway." (PMID 26682910, 2015). "Following initial comparison with other tumor types, microRNA profiles were then investigated in detail in pilocytic astrocytomas, all of which contained the KIAA1549:BRAF gene fusion." (PMID 26682910, 2015). "Group II contained tumors that were largely pilocytic astrocytomas, but with foci of gangliocytic differentiation; 82% of these tumors were characterized by a KIAA1549-BRAF fusion gene, which is the hallmark of pilocytic astrocytomas." (PMID 24529209, 2014). "KIAA1549:BRAF fusion positive pilocytic astrocytomas also occur less frequently with increasing age." (PMID 24716189, 2014). "KIAA1549-BRAF is a recurrent oncogenic driver in sporadic pilocytic astrocytoma, but is described here in a spindle cell neoplasm for the first time." (PMID 24422672, 2014). "What are the implications of this case for treating tumors that express the KIAA1549-BRAF fusion such as pediatric pilocytic astrocytomas?" (PMID 24422672, 2014). "Infratentorial posterior fossa pilocytic astrocytomas tend to display a high frequency of the KIAA1549:BRAF fusion." (PMID 24716189, 2014). "Another genetic aberration in BRAF in addition to BRAF V600E point mutations that leads to increased kinase activity in low- and high-grade pediatric brain tumors is a fusion protein of KIAA1549:BRAF that is found in the majority of pilocytic astrocytomas." (PMID 23717811, 2013). "Two-thirds of pilocytic astrocytomas, a low-grade pediatric glioma, contain a translocation within the BRAF gene called KIAA1549:BRAF that causes an overactivation of the MEK/MAPK signaling cascade." (PMID 23717811, 2013). "In four patients, with a pilocytic astrocytoma, the transcript KIAA1549-BRAF fusion was present." (PMID 40731067, 2025). "Treatment of pilocytic astrocytoma (PA)-derived KIAA1549:BRAF fusion- (DKFZ-BT66, DKFZ-BT308) or BRAFV600E-driven cells (DKFZ-BT314) in proliferating state (induced by SV40-TAg) or senescent state (no SV40-TAg induction) did not reduce viable cell numbers compared to untreated cells." (PMID 38630384, 2024). "Additionally, the variations in the targeted genes: TNS1, FAM212B and KIAA1549 have led to the diseases such as malignant tumors of the breast, Crohn’s disease and Pilocytic astrocytoma, respectively." (PMID 38674383, 2024).
pilocytic astrocytoma (continued). "One diffuse astrocytoma and 43 pilocytic astrocytomas were positive for the KIAA1549-BRAF fusion." (PMID 35363819, 2022). "Case 19 had a pilocytic astrocytoma-like glial component and KIAA1549-BRAF fusion." (PMID 36290809, 2022). "In 5/11 cases of pilocytic astrocytoma a BRAF-KIAA1549 fusion was detected by the panel." (PMID 36397144, 2022). "In a similar fashion, the V600E mutation in BRAF (coded by the BRAF gene) highly correlates with a poorer prognosis and overall survival across a broad spectrum of pediatric LGG, while the KIAA1549-BRAF gene fusion aids in the diagnosis of pilocytic astrocytomas (PA)." (PMID 35363819, 2022). "Moreover, KIAA1549-BRAF fusion detected for two adult SIA patients was previously relatively frequently found in pediatric pilocytic astrocytomas and was reported to confer a clinically less aggressive phenotype in pediatric low-grade astrocytoma." (PMID 35387112, 2022). "To surmount this barrier, we leveraged human induced pluripotent stem cell (hiPSC) engineering to generate low-grade gliomas (LGGs) harboring the two most common pediatric pilocytic astrocytoma-associated molecular alterations, NF1 loss and KIAA1549:BRAF fusion." (PMID 35986378, 2022). "At least one molecular alteration was found in 87.5% (14/16) and 71% (17/24) of brain and spinal grade I pilocytic astrocytoma cases, respectively (Fisher test: p = 0.27) with the KIAA1549-BRAF fusion being the most common molecular alteration found in both locations." (PMID 32771057, 2020). "Grade I pilocytic astrocytomas were characterized by KIAA1549-BRAF fusions in both locations." (PMID 32771057, 2020). "Due to its predilection for arising in highly circumscribed histologies (pilocytic astrocytoma) and in surgically amenable locations (cerebellum), tumors with a KIAA1549-BRAF fusion are often amendable to complete surgical resection and have excellent overall survival and rarely progress." (PMID 32164789, 2020). "Those pilocytic astrocytomas which do not harbour KIAA1549–BRAF fusion mutations, have been found to have mutations in genes encoding constituents of the MAP kinase pathway, including FGFR1 and NTRK gene family, NF1, PTPN11, KRAS and RAF1." (PMID 29098416, 2018). "We also employed RNA-seq-based methodology (ArcherDx) to identify fusion transcripts in six of our samples, with the initial aim of assessing whether the KIAA1549-BRAF fusion event commonly found in pilocytic astrocytomas exhibits similar prevalence in PLNTYs." (PMID 27812792, 2017). "In addition, one pilocytic astrocytoma tumor harbored the KIAA1549-BRAF fusion, which is the most frequent MAPK pathway alteration in this tumor type." (PMID 28468611, 2017). "In addition, MLN2480 has recently been shown to suppress pERK and cell proliferation in short term cultures of primary pilocytic astrocytoma cells that were confirmed as positive for the KIAA1549:BRAF fusion gene." (PMID 28002790, 2017). "Importantly, BRAF alterations (V600E mutations and KIAA1549-BRAF fusions) were distributed across multiple diagnostic groups—PLNTY, ganglioglioma, and pilocytic astrocytoma—each of which exhibited a distinct methylation signature." (PMID 27812792, 2017). "Interestingly, in murine models of pilocytic astrocytoma, the KIAA1549-BRAF fusion hyperactivates the mTOR pathway, as does loss of PTEN." (PMID 24422672, 2014). "The KIAA1549 gene is often fused to the BRAF in cases of pilocytic astrocytoma." (PMID 25423363, 2014). "Several studies suggest that, unlike the BRAF V600E mutation, the KIAA1549:BRAF fusion is associated with an infratentorial location for pilocytic astrocytomas." (PMID 23717811, 2013). "KIAA1549-BRAF was identified in 120 patients and this rearrangement has been established to be frequently found in pilocytic astrocytoma." (PMID 34745213, 2021). "These include SVs around KIAA1549 in pilocytic astrocytomas, likely resulting in BRAF-KIAA1549 fusions." (PMID 33831375, 2021).